LAG3 (lymphocyte activating 3)
Diseases named in the same sentence as LAG3 in open-access papers (continued):
Sharing a sentence is not in itself a finding about the gene and the disease.
colitis (15 papers, 2014 to 2025). Inflammation of the colon. "CTLA-4 inhibitors are more associated with colitis, rash, hepatitis, and hypophysitis, while LAG-3 inhibitors are more often associated with colitis, hepatitis, rash, endocrinopathy, and neuropathy." (PMID 38539558, 2024). "We also reported that Lag3-deficient Treg cells fail to suppress homeostatic proliferation and T cell-induced colitis development and that Lag3 expression in Treg cells is indispensable for in vivo suppressive function in autoimmune inflammation." (PMID 41177809, 2025). "Ctla4 was the most highly upregulated checkpoint gene in all the colitis models, with less pronounced changes in the expression of Pdcd1, Lag3, Vsir and Havcr2." (PMID 39496592, 2024). "Lag3 has also been suggested to be expressed by regulatory T cells and able to suppress gut macrophages and mucosal T cells in colitis, further suggesting that the cleavage of Lag3 in IBD is detrimental." (PMID 36558958, 2022). "During colitis, Lag3 is thought to be expressed by regulatory T cells and can restrain gut resident macrophages and innate lymphoid cells." (PMID 36558958, 2022). "LAG-3 on Tregs was also highlighted in an innate-like cell 3-driven experimental inflammatory model of colitis, where LAG-3+ Tregs specifically targeted CX3CR1+ macrophages, decreasing their production of IL-23 and IL-1β, ameliorating disease." (PMID 34907325, 2021). "Approximately 2% of the CD4+CD25− T-cellpopulation in the spleen express LAG3.These LAG3+ Tregproduce high levels of interleukin(IL)-10 and are suppressive in a murine model of colitis in anIL-10-dependent manner." (PMID 25695838, 2015). "Our colitis data further support the notion that LAG-3 KO cells are relatively resistant to suppression, though these experiments cannot examine their absolute potential to be suppressed without other controls." (PMID 25372844, 2014). "The relative resistance of LAG-3 KO responders to be suppressed was observed in three separate models: 1) during HP 2) in vitro and 3) in a fairly well established in vivo colitis model." (PMID 25372844, 2014). "It must be noted that, in two patients, anti‐PD1 antibodies were used in combination with an anti‐LAG3 antibody, which may also induce, while rarely, diarrhoea and colitis." (PMID 40769948, 2025). "Whether the expression of LAG-3 on Tr1 cells is functionally important has not been determined, but it was recently shown that IL-27 induced expression of LAG-3 on Foxp3+ Treg cells had suppressive functions in a colitis model in mice." (PMID 26866695, 2016). "While these findings do not demonstrate the absolute susceptibility of LAG-3 KO responders, they do demonstrate that the LAG-3 KO responders are relatively more resistant to suppression than their WT counterparts in an in vivo colitis model, and confirm our previous in vitro results." (PMID 25372844, 2014). "LAG-3 KO responder cells, by contrast, were relatively resistant to suppression this model; young mice gained only a minimal amount of weight over the course of the experiment, and demonstrated an intermediate level of colitis upon histological examination." (PMID 25372844, 2014). "GeoMx analysis confirmed the infiltration of colon in mice that developed colitis after transfer of toxic IgG and identified a colitis-specific gene signature with upregulation of immune cells expressing immune checkpoint inhibitors, such as LAG3, TIM-3, PD-1(PD-L1), and CTLA-4." (PMID 36058945, 2022). "To test whether LAG-3 modulates the ability of Tresp to be suppressed in a potentially more physiologically relevant context, we turned to the well-described in vivo model of induced colitis." (PMID 25372844, 2014). "In terms of overall colitis score, mice receiving LAG-3 KO responder cells plus Treg showed slightly more colitis then mice receiving WT responders and no Treg at all, although that increase was not statistically significant." (PMID 25372844, 2014).
colitis (continued). "RAG1 KO mice receiving LAG-3 KO responders + Treg displayed a generally intermediate phenotype, i.e. their colitis was less severe than those receiving no Treg at all, but slightly more severe (especially in terms of cell numbers) than mice receiving WT Treg and WT responders." (PMID 25372844, 2014).
parasitemia (15 papers, 2016 to 2026). "Recently, several studies have reported that immune checkpoints, including PD-1, CTLA-4, LAG-3, TIM-3, TIGIT, etc., were associated with immune tolerance and immune escape in parasitic infections." (PMID 39456030, 2024). "From this, we identified 26 common DEGs downregulated in Tr1 cells from both parasitic diseases, including Ccr7, Tcf7, and Bcl6, as well as 29 upregulated DEGs, including Il10, Havcr2, Prdm1, Ccr2, Ccr5, Maf, and Lag3." (PMID 37917177, 2023). "LAG3 deficiency can restore the Th1 immune response of CD4+ T cells and effectively defend against parasitic infections at a late stage." (PMID 37172058, 2023). "Slightly higher Ab titers were nevertheless measured in day 72 sera from anti-LAG-3-treated PD-L1-/- mice, in line with the observed delayed parasitemia results." (PMID 33519801, 2020). "LAG-3 blockade in WT mice promoted only a partial reduction of parasitemia compared to co-blockade with anti-PD-L1 mAb." (PMID 33519801, 2020). "Taken together, we favor the interpretation that LAG-3 neutralization leads to improved control of parasitemia by rescuing functional effector CD4+ T cell responses, independent of parasite-specific Ab responses." (PMID 33519801, 2020). "LAG-3 blockade in PD-L1-/- mice promoted reduced parasitemia to an extent that was comparable to that of WT mice treated with anti-PD-L1/LAG-3 mAbs." (PMID 33519801, 2020). "To gain further insight into how LAG-3 blockade contributed to reduced blood parasitemia, we next investigated which cells express the LAG-3 receptor during Py infection." (PMID 33519801, 2020). "LAG-3 has been described as an essential next-generation immune checkpoint receptor proposed as a therapeutic target against cancer, autoimmune and inflammatory diseases, parasitic infections, and acute and chronic viral infections." (PMID 36680187, 2023). "We next sought to determine the potential of LAG3 and TIM3 as clinical targets in human parasitic disease." (PMID 37917177, 2023). "For example, parasite infection (Nb) and mite allergen (HDM) induced predominantly IL-10-producing LAG3+CD49b+ T cells that are CD4+ with very few that are CD8+." (PMID 30510554, 2018). "IL-10 production can be significantly elevated in the pulmonary mucosa during the late stages of parasitic infection by Nippostrongylus brasiliensis (Nb), predominantly by CD4+ T cells that are LAG3/CD49b double positive." (PMID 30510554, 2018). "Interestingly, blood parasitemia was comparable in anti-LAG-3/PD-1 versus anti-LAG-3 treated PD-L1-/- mice, suggesting that inhibition of LAG-3 is dominant over that of PD-1/PD-L2." (PMID 33519801, 2020). "LAG-3 blockade in CD8+ T cell-depleted PD-L1-/- mice enhanced the control and clearance of blood parasitemia similarly to that of undepleted control groups, indicating that anti-LAG-3 blockade does not act on CD8+ T cells." (PMID 33519801, 2020). "In contrast, neither LAG-3 nor Tim-3 expression showed a correlation with parasitemia." (PMID 29555909, 2018). "In contrast, CD4+ T cell-depleted mice failed to control parasite growth and developed chronic parasitemia, losing >10% of initial body weight 20 days post-infection whether treated with anti-LAG-3 or control isotype Abs, and consistent with their requirement for Py parasite clearance." (PMID 33519801, 2020). "Along this hypothesis, we found a slightly delayed blood parasitemia clearance in anti-LAG-3-treated, CD8+ T cell-depleted PD-L1-/- mice, and a mild increase in cytokines secreted after ex vivo stimulation of CD8+ T cells isolated from anti-LAG-3-treated Py-infected mice." (PMID 33519801, 2020).
sarcoma (15 papers, 2020 to 2024). A usually aggressive malignant neoplasm of the soft tissue or bone. "Multiple assessments of potential biomarkers such as PD-1/PD-L1, LAG-3 or TIM-3 expression in sarcomas have been inconclusive when correlating them with treatment outcome." (PMID 36765863, 2023). "A basket phase II study of anti-PD1 spartalizumab plus anti-LAG3 LAG525 in advanced solid tumors included a cohort of 10 patients with advanced sarcoma, reporting a disease control rate (DCR) of 40% at 24 weeks." (PMID 37190214, 2023). "However, detecting a significant positive correlation between PDL-1 staining and TIM-3 and LAG-3 staining also holds promise for finding effective targetable combination therapies that can prolong survival in sarcoma patients in the future." (PMID 38930150, 2024). "High levels of tumour cell expression of LAG3, TIM3, and VTCN1 have been reported in multiple cancer types, including sarcoma, often in association with a worse clinical outcome, indicating an active role in promoting an immunosuppressive, tumour-promoting microenvironment." (PMID 35327375, 2022). "Recent studies to define characteristics of sarcomas which predict response or resistance to immunotherapy have included those examining tumor mutational burden, the tumor microenvironment (TME), and tumoral expression of immune checkpoint proteins PD-1, PD-L1, BTLA-4, CTLA4, and LAG3." (PMID 36826126, 2023). "Such therapeutic targets in sarcomas include T cell Immunoglobulin and Mucin-domain containing-3 (TIM-3), Leukocyte Activation Gene-3 (LAG-3), and T cell Immunoreceptor with Ig and ITIM domains (TIGIT)." (PMID 34440251, 2021). "Even LAG3 showed a significantly higher expression (p < 0.05) in EMT-high tumors of all cancers, except SKCM, TGCT, and Sarcoma (SARC)." (PMID 35096592, 2021). "Co-expression of TIM-3 with other immune checkpoints such as lymphocyte activating 3 (LAG3) and PD-1 on T cells has been observed in sarcoma patient samples; however, its expression on TAMs in sarcoma has not been explored." (PMID 33381449, 2020). "As ongoing and future research uncovers more about the role of LAG-3 in suppressing T cell activation and the molecular mechanisms governing this, we would then be able to better understand its place in cancer immunotherapy and as a predictive biomarker for ICI response in sarcomas." (PMID 37612756, 2023). "PTPN2‐deficient CD8+ HER‐2 CAR T cells were more activated, as assessed by the expression of CD44, CD25, PD‐1 and LAG‐3, after overnight incubation with HER‐2‐expressing 24JK (24JK‐HER‐2) sarcoma cells, but importantly, not HER‐2‐negative 24JK control cells (Fig EV1B)." (PMID 31803974, 2020).
cutaneous melanoma (14 papers, 2020 to 2025). A primary melanoma arising from atypical melanocytes in the skin. "Our findings demonstrated that elevated LAG3 expression is significantly associated with favorable prognosis in patients with cutaneous melanoma (SKCM), and it may be a potential biomarker for SKCM." (PMID 38115039, 2023). "In cutaneous melanoma treated with anti–PD-1, LAG-3 positivity aligns with ICI responsiveness and longer PFS, whereas in ocular melanoma, high LAG-3 expression is instead associated with adverse outcomes." (PMID 40981345, 2025). "Both showed an increase in LAG3 expression, while LAG3 was decreased in 6 of 11 cutaneous melanoma (CM) patients." (PMID 40311102, 2025). "Another anti-LAG3 therapeutic approach proved efficacious with a high safety profile when it was combined with anti-PD-1 blockade in cutaneous melanoma patients." (PMID 34503258, 2021). "Farshidfar and colleagues identified that acral melanomas have a lower overall immune cell infiltrate as compared to traditional cutaneous melanoma, but of these infiltrates, PD-1, LAG-3, CTLA-4, VISTA, TIGIT, and ADORA2 were highly expressed, introducing new possible therapeutic targets." (PMID 39001457, 2024). "This suggests that PD-1 and LAG-3 expression could be affected by CD163-positive TAMs in cutaneous melanoma." (PMID 32756500, 2020). "Our results may support combinatory immunotherapeutic strategies, especially for targeting anti-PD-1 and/or anti-LAG-3 with anti-CD163 or macrophage inhibitors in advanced cutaneous melanoma." (PMID 32756500, 2020). "The prognostic significance of LAG-3 in cutaneous melanoma was reported." (PMID 32756500, 2020). "IDO1 and LAG3 overexpression, which was evident in CYT-high skin melanomas, provides an alternative immunosuppressive barrier that is needed to hamper the antitumor activity of CTL and NK cells, in these tumors." (PMID 33779796, 2021). "Major histocompatibility complex class II (MHC II) molecules, which are highly expressed in cutaneous melanomas, represent the canonical ligands of LAG-3, as they do for CD4, however, the proline-rich D1 domain allows LAG-3 to bind with higher affinity to MHC II than to CD4." (PMID 37004702, 2023). "However, also the relationship between the expression of CD163 and LAG-3 in cutaneous melanoma has not yet been investigated." (PMID 32756500, 2020).
follicular lymphoma (13 papers, 2017 to 2025). Follicular lymphoma is a form of non-Hodgkin lymphoma characterized by a proliferation of B cells whose nodular structure of follicular architecture is preserved. "In follicular lymphoma, high expression of LAG-3 is associated with poorer patient prognosis and T-cell failure." (PMID 35601491, 2022). "Overexpression of LAG-3 is linked to worse clinical outcomes in follicular lymphoma." (PMID 41357215, 2025). "Elevated LAG‐3 expression has been linked to poor prognosis in follicular lymphoma." (PMID 40091778, 2025). "In follicular lymphoma overexpression of LAG-3 is associated with poor clinical outcomes." (PMID 36077354, 2022). "In follicular lymphoma, LAG-3 expression distinguishes functionally exhausted intratumoral PD-1+ T cells from PD-1+LAG-3− cells, which remain activated and immunologically competent." (PMID 41300994, 2025). "In follicular lymphoma, LAG‐3 expression on tumor‐infiltrating lymphocytes under chronic immune stimulation has been linked to impaired CD8+ T lymphocytes." (PMID 40091778, 2025). "In follicular lymphoma, it has been reported that intratumoral PD-1–positive/LAG-3-positive T cells are functionally suppressed and that intratumoral T-cell function is enhanced when both PD-1 and LAG-3 are blocked." (PMID 36232824, 2022). "Such a situation was described in follicular lymphoma, with T cells forming a heterogenic population: some of the T cells which expressed PD-1 were also LAG3 positive." (PMID 34503258, 2021). "In follicular lymphoma, a subset of intratumoral PD-1+ T cells were also found to be LAG-3+, which correlated with functionally exhausted T cells and inferior outcome." (PMID 31007846, 2019). "Co-expression of PD-1 and LAG-3 observed in exhausted TILs present in follicular lymphoma were found to be responsive to combined blockade of both PD-1 and LAG-3." (PMID 31007846, 2019). "In addition, LAG-3 expression in TILs was also demonstrated in follicular lymphoma (FL) and Hodgkin’s lymphoma(HL) and also showed good response to dual blockade PD-1/LAG-3 treatment." (PMID 36561512, 2022).
head and neck cancer (11 papers, 2020 to 2025). A primary or metastatic malignant neoplasm affecting the head and neck. "Some checkpoints, such as the co-inhibitory checkpoint and marker for immune exhaustion lymphocyte-activation gene 3 (LAG-3), are associated with clinical characteristics and disease outcomes such as in advanced head and neck cancer." (PMID 40761788, 2025). "On the contrary, high levels of soluble LAG-3 were association with poor PFS and OS in advanced head and neck cancer." (PMID 34691076, 2021). "Interestingly, chemo-radiation has been shown to increase the proportion of CD4 + LAG-3+ expressing cells in head and neck cancer patients demonstrating that this effect may be clinically relevant and detectable." (PMID 32299365, 2020). "Indeed, numerous ongoing clinical trials are investigating the efficacy of ICIs targeting LAG-3 and TIM-3 in various cancer types including head and neck cancer (e.g., NCT04811027, NCT05287113), especially in combination with PD-1 antibodies." (PMID 39769271, 2024). "However, no LAG-3 and/or TIM-3 inhibitors are approved for the treatment of head and neck cancer so far, so further clinical studies are needed." (PMID 39769271, 2024).
osteosarcoma (11 papers, 2015 to 2025). A usually aggressive malignant bone-forming mesenchymal neoplasm, predominantly affecting adolescents and young adults. "In this study, we noted a higher expression level of the ICGs (CTLA4, CD274, PDCD1C, HAVCR2, and LAG3) in the osteosarcoma patients categorized into the low‐risk group, which suggested that these patients could gain more benefits from the immune checkpoint blockade therapy." (PMID 36129020, 2023). "Preclinical models of osteosarcoma have demonstrated that LAG-3 blockade, when combined with PD-1 inhibition, results in increased tumor regression in murine models, further supporting the therapeutic potential of targeting LAG-3 in osteosarcoma." (PMID 40170852, 2025). "The phenomenon of T cell exhaustion is well-documented in osteosarcoma, with tumor-infiltrating T cells expressing high levels of PD-1, TIM-3, and LAG-3—markers associated with dysfunctional and anergic T cells." (PMID 40170852, 2025). "In this study, we characterized the expression of PD-1, PD-L1, TIM-3, Galectin 9, LAG-3, MHC Class II on diagnostic tissue samples from patients with Ewing sarcoma and osteosarcoma." (PMID 35938052, 2021). "Previous studies have also found that CD44, CD40, PDCD1LG2, LAG3, and HAVCR2 can be immunotherapeutic targets for osteosarcoma." (PMID 38071320, 2023). "In this study, we characterized the expression of PD-1, LAG-3, Tim-3, and their respective ligands PD-L1, major histocompatibility complex class II (MHC class II), Galectin-9 in children with Ewing sarcoma and osteosarcoma at diagnosis." (PMID 35938052, 2021). "It was found that there was a significant relationship of the risk score with important immune checkpoints expressions (CTLA4, PDL1, TIM3, LAG3, TIGIT) in osteosarcoma patients." (PMID 34335109, 2021). "Additionally, osteosarcoma cells exploit immune checkpoint pathways, such as PD-1/PD-L1, CTLA-4, lymphocyte activation gene-3(LAG-3), and T cell immunoglobulin and mucin domain-containing protein 3(TIM-3), to evade immune surveillance." (PMID 40170852, 2025). "In addition, specific immune checkpoint inhibitors are being explored as new immunotherapeutic strategies for osteosarcoma, such as CTLA-4, LAG3, TIGIT, and PD-1/L1 (Wang S.-D." (PMID 34899864, 2021). "However, newer checkpoint molecules such as LAG-3, TIM-3, T cell immunoreceptor with Ig and ITIM domains (TIGIT), V-domain Ig suppressor of T cell activation (VISTA), and B7-H3 (CD276) have gained increasing attention as potential targets in osteosarcoma." (PMID 40170852, 2025). "Relatively low expression levels of CTLA4, HAVCR2, LAG3, and PDCD1LG2 can be observed in the group of patients with metastasis (p < 0.05), which may indicate and predict a poor prognosis in patients with osteosarcoma." (PMID 38256356, 2024). "Second, osteosarcoma tumor cells at diagnosis did not express any checkpoint receptors and ligands except Galectin-9, and non-tumor cells were also negative for PD-1, PD-L1, and LAG-3, suggesting that these tumors may be resistant to currently available checkpoint inhibitors if used at diagnosis." (PMID 35938052, 2021).